SCIN (scinderin)
Description:
Ca(2+)-dependent actin filament-severing protein that has a regulatory function in exocytosis by affecting the organization of the microfilament network underneath the plasma membrane. Severing activity is inhibited by phosphatidylinositol 4,5-bis-phosphate (PIP2) (By similarity). In vitro, also has barbed end capping and nucleating activities in the presence of Ca(2+). Required for megakaryocyte differentiation, maturation, polyploidization and apoptosis with the release of platelet-like particles. Plays a role in osteoclastogenesis (OCG) and actin cytoskeletal organization in osteoclasts (By similarity). Regulates chondrocyte proliferation and differentiation (By similarity). Inhibits cell proliferation and tumorigenesis. Signaling is mediated by MAPK, p38 and JNK pathways.
Synonyms: KIAA1905
Tractability: Small molecule: it has a high-quality binding pocket. Antibody: the Human Protein Atlas places it where antibodies can reach. PROTAC: ubiquitination databases record sites on it.
Gene: Protein-coding gene on chromosome 7 (12,570,577 to 12,660,182, forward strand). Ensembl gene ENSG00000006747.
Subcellular location: Cytoplasm, cytoskeleton; Cell projection, podosome
Subcellular location (Human Protein Atlas): Plasma membrane; Cytosol
Gene Ontology:
Molecular function: protein binding; 1-phosphatidylinositol binding; actin binding; actin filament binding; calcium ion binding; phosphatidylinositol-4,5-bisphosphate binding; phosphatidylserine binding
Biological process: actin filament capping; actin filament severing; negative regulation of cell population proliferation; positive regulation of actin nucleation; positive regulation of apoptotic process; positive regulation of megakaryocyte differentiation; actin nucleation; actin polymerization or depolymerization; barbed-end actin filament capping; calcium-ion regulated exocytosis; central nervous system development; positive regulation of secretion; regulation of chondrocyte differentiation
Cellular component: extracellular exosome; cell cortex; cytoplasm; brush border; cytoskeleton; podosome
Genetic constraint (gnomAD): Loss-of-function variants: 67 observed, 70.67 expected, observed/expected ratio (o/e) 0.95, 90% interval 0.78 to 1.16. The upper end of that interval is the gene's LOEUF score, 1.16, which puts it in group 5 of 6, group 1 being the genes least tolerant of losing a copy. Missense variants: 950 observed, 770.33 expected, observed/expected ratio (o/e) 1.23, 90% interval 1.17 to 1.3. Synonymous variants: 329 observed, 285.81 expected, observed/expected ratio (o/e) 1.15, 90% interval 1.05 to 1.26.
Homologues: Orthologues: chimpanzee SCIN (99% identical), macaque SCIN (98% identical), dog SCIN (93% identical), pig SCIN (93% identical), mouse Scin (91% identical), guinea pig SCIN (90% identical), rabbit SCIN (89% identical), rat Scin (77% identical), tropical clawed frog scin (74% identical), zebrafish scin (71% identical), Drosophila melanogaster Gel (37% identical), Caenorhabditis elegans gsnl-1 (27% identical). Paralogues in human: GSN (60% identical), AVIL (49% identical), VIL1 (47% identical), VILL (38% identical), FLII (31% identical), SVIL (27% identical), CAPG (23% identical).
Diseases named in the same sentence as SCIN in open-access papers:
SCIN is named in the same sentence as 37 diseases in open-access papers, as found by Europe PMC text mining. Sharing a sentence is not in itself a finding about the gene and the disease. The quoted sentences say what the papers report.
gastric cancer (9 papers, 2018 to 2025). A primary or metastatic malignant neoplasm involving the stomach. "In gastric cancer, a high level of SCIN expression was associated with a poor prognosis of patients, and enhanced the proliferation, migration, invasion, and metastasis of gastric cancer cells." (PMID 36291348, 2022). "It has been reported that the expression of SCIN is associated with the depth of invasion and lymph node metastasis of human gastric cancer and is related to a poor prognosis." (PMID 36291348, 2022). "SCIN was highly expressed in gastric cancer tissues and the level of expression associated with the depth of tumor invasion, lymph node metastasis, and poor overall survival." (PMID 31736743, 2019). "However, in other research projects, the SCIN expression was low and associated with poor progress in acute myeloid leukemia, hepatocellular carcinoma, and gastric cancer." (PMID 36291348, 2022). "Our data suggest that miR-301a-5p acts as an oncogene by suppressing the expression of SCIN and regulating gastric cancer progression via STAT3 and NF-κB signaling." (PMID 34405002, 2021). "Scinderin and Gelsolin genes play key roles in gastric cancer initiation, progression, and invasion." (PMID 32636728, 2020). "SCIN knockdown inhibited the invasion and metastasis of gastric cancer cells and restrained the filopodium formation and Cdc42 expression." (PMID 31736743, 2019). "Another study found high levels of SCIN expression in gastric cancer tissue correlated with poor prognosis." (PMID 31736743, 2019). "In agreement with our report, SCIN expression levels were shown to correlate with poor overall survival in patients with gastric cancers, and silencing of SCIN effectively suppressed the migratory and invasive capabilities and tumourigenicity." (PMID 29744289, 2018). "SCIN enhances the progression of gastric cancer by modulating STAT3 and NF‐Κb signaling pathways." (PMID 39964147, 2025). "It is reported that SCIN acts as a tumor suppressor in gastric cancer." (PMID 38201443, 2023). "Moreover, a SCIN knockout reduces the migration ability of gastric cancer cells through regulating epithelial mesenchymal transformation (EMT)." (PMID 36291348, 2022). "Furthermore, the mechanistic interaction between miR-301a-5p and SCIN in regulation of gastric cancer cell phenotype was revealed." (PMID 34405002, 2021). "Furthermore, SCIN promoted the invasion and metastasis of gastric cancer cells through activating the Cdc42 pathway to increase the formation of filopodia." (PMID 31736743, 2019). "In gastric cancer, the overexpression of SCIN is associated with poor overall survival rate, and it changes significantly in stages I and IV, stage II and IV, and stage III and IV, which may promote the progression of gastric cancer by regulating STAT3 and NF-κB signaling." (PMID 39108273, 2024). "In the gastric cancer cell line SGC-7901, the knockdown of SCIN can inhibit the migration and invasion ability of tumor cells by inhibiting the epithelial–mesenchymal transition." (PMID 38201443, 2023). "In the present study, we investigated the relationship between miR-301a-5p and SCIN and their regulatory effects via STAT3 and NF-κB signaling on the proliferation and motility of gastric cancer cell lines." (PMID 34405002, 2021).
prostate carcinoma (7 papers, 2015 to 2025). A carcinoma that arises from epithelial cells of the prostate gland. "Previously, we reported a positive association in prostate cancer between poor differentiation status and scinderin (SCIN) 8, which is drastically upregulated in this condition." (PMID 29744289, 2018). "Suppression of SCIN inhibits proliferation and induces cell cycle arrest in human prostate cancer cells." (PMID 39964147, 2025). "SCIN not only promotes the survival of prostate cancer cell by stabilizing EGFR and MEK/ERK signals, but also enhances the proliferation of lung cancer cell, and exerts as a functional apoptosis regulator in the hepatocellular carcinogenesis." (PMID 39108273, 2024). "A previous study revealed that SCIN suppression was related with the inhibited proliferation of human prostate cancer." (PMID 39108273, 2024). "In prostate cancer cell lines, silencing the expression of SCIN can inhibit the proliferation and clonogenic ability of prostate cancer cells and promote the apoptosis of castration-resistant prostate cancer cells." (PMID 38201443, 2023). "Another study found SCIN was highly expressed in prostate cancer and promoted prostate cancer cell proliferation by the EGFR and MEK/ERK singling pathway." (PMID 36291348, 2022). "In the present study, we demonstrated that SCIN, which is significantly overexpressed in prostate carcinoma, acted as a tumour growth promoter in prostate cancer." (PMID 29744289, 2018). "Our previous study showed that the SCIN protein level was negatively correlated with the differentiation status in prostate cancer." (PMID 29744289, 2018). "Of these 8 secretion-related genes, 5 genes (FKBP1B, SCIN, SMPD3, STEAP2, and TRIM36) has been associated with prostate cancer and hyperplasia." (PMID 26113971, 2015). "Thus, in order to address the function of Scinderin in prostate carcinoma cells, its expression was knocked down in the PC3 cell, a prostate carcinoma cell line, using lentivirus-mediated RNAi." (PMID 32636728, 2020). "To assess whether other molecules in the prostate cancer cell were affected by the expression of SCIN, we preliminarily used a gene expression chip to screen PC‐3 cells (unpublished data) and found that the EGFR and RPS6KA2 expression was regulated by SCIN." (PMID 29744289, 2018). "Thus, we conclude that SCIN promotes prostate cancer cell survival by stabilising EGFR and MEK/ERK signalling." (PMID 29744289, 2018). "Nevertheless, our studies of SCIN and its functions may reveal novel strategies for prostate cancer management." (PMID 29744289, 2018). "Consistently, SCIN has been proposed as the potential target in different tumor types, such as CRC and prostate cancer." (PMID 39108273, 2024).
breast carcinoma (5 papers, 2022 to 2025). "A growing number of changes have been identified in the genome and the epigenome of breast cancer cell lines, with the upregulation of SCIN and GIRK1 playing a key role in promoting proliferation and inhibiting apoptosis." (PMID 40946111, 2025). "We observed elevated expression in other key regions, such as EGFR and SCIN, which are well-known to be highly expressed in breast cancer resistance." (PMID 40946111, 2025). "Genes identified included novel genes such as HPGD, FASN and KRT81, as well as SCIN and TPM1 which have already been confirmed in acquired drug resistance mechanisms associated with HER2-positive breast cancer." (PMID 40946111, 2025). "It is reported that SCIN is a novel oncogene that facilitates the proliferation and suppresses apoptosis of breast cancer cells." (PMID 39108273, 2024). "Further, the Cistrome DB analysis showed that the GRHL2 protein had regulatory potential for SCIN in breast cancer cells." (PMID 38201443, 2023). "There is a study that demonstrates that SCIN knockdown inhibits breast cancer cell proliferation and induces apoptosis." (PMID 38201443, 2023). "SCIN expression inhibition significantly leads to cell apoptosis and the reduced proliferation speed of the cells in breast cancer cell lines." (PMID 38201443, 2023). "Furthermore, SCIN expression is observed to be higher in breast cancer tissues than in benign breast tissues." (PMID 38201443, 2023). "Furthermore, SCIN was increased in breast cancer and the knockdown of SCIN could inhibit breast cancer cell proliferation and induce apoptosis." (PMID 36291348, 2022). "It is reported that SCIN and Cofilin−1 (CLF1) are the members of the actin-binding protein family, both of which are overexpressed in breast cancer and significantly correlated with tumor stage and lymph node metastasis." (PMID 39108273, 2024). "In the GSM2970418 data including the breast cancer cell and epithelium, the regulatory score was 1.735 of GRHL2 for SCIN." (PMID 38201443, 2023). "Notably, genes such as SCIN and EGFR, already known to be involved in HER2-positive breast cancer, were confirmed, reinforcing the validity of our approach." (PMID 40946111, 2025).
leukemia (5 papers, 2013 to 2024). A malignant (clonal) hematologic disorder, involving hematopoietic stem cells and characterized by the presence of primitive or atypical myeloid or lymphoid cells in the bone marrow and the blood. "Another study has suggested that the expression of SCIN inhibits the proliferation and tumor formation of human megakaryoblastic leukemia cells in nude mice." (PMID 39108273, 2024). "SCIN expression in megakaryoblastic leukemia cells promoted cell apoptosis and impaired cell proliferation and tumor formation, which is contrary to our study and others." (PMID 31736743, 2019). "An anti-tumor role for SCINDERIN has been described based on its capacity to induce differentiation and apoptosis in megakaryoblastic leukemia cells that overexpress SCINDERIN." (PMID 24330498, 2013). "Interestingly, SCIN overexpression inhibited tumor proliferation in vitro and tumorigenesis in vivo in megakaryoblastic leukemia cells, with similar effects reported in another type of leukemia." (PMID 35490173, 2022). "More specifically, the lack of SCIN in megakaryoblastic leukemia cells and, consequently, the lack of proper actin dynamics, might be related to the inability of these cells to enter into differentiation and maturation pathways." (PMID 28205611, 2017).
colorectal cancer (3 papers, 2019 to 2022). A primary or metastatic malignant neoplasm that affects the colon or rectum. "A high SCIN expression correlated with liver metastasis and poor progress in colorectal cancer." (PMID 36291348, 2022). "A colorectal cancer study demonstrated that SCIN knockdown significantly reduced DIAPH1 expression and SCIN served as an independent predictor of poor prognosis, which implies that high DIAPH1 expression may be associated with poor prognosis." (PMID 34631544, 2021).
glioma (3 papers, 2018 to 2024). A benign or malignant brain and spinal cord tumor that arises from glial cells (astrocytes, oligodendrocytes, ependymal cells). "In this study, we found that SCIN was upregulated in gliomas, and a high expression of SCIN was associated with a poor survival." (PMID 36291348, 2022). "We revealed the expression of SCIN was higher than normal brain tissues and associated with glioma grade." (PMID 36291348, 2022). "To further investigate the potential cause of the association between SCIN expression and the EMT of a glioma, we identified SCIN and MMP2/9 in our clinical tissue samples by IHC and Western blot analysis." (PMID 36291348, 2022). "Then, we observed that the missense mutation or amplification of SCIN occurred at a low rate in gliomas by the cBioportal." (PMID 36291348, 2022). "Moreover, CGGA analysis showed that SCIN expression was negatively associated with survival in glioma patients in three CGGA microarray datasets." (PMID 36291348, 2022). "The similar expression pattern of SCIN was found in glioma and the SCIN was correlated with the poor prognosis." (PMID 39108273, 2024). "Then, the expression of SCIN in glioma and normal brain tissues was examined in the Oncomine database." (PMID 36291348, 2022). "In our present study, we analyzed the expression and prognosis of SCIN in a large cohort of glioma patients from TCGA, CGGA, and our hospital samples." (PMID 36291348, 2022). "Our research is the first to propose the expression of SCIN in glioma, and also supports the oncogenic role of SCIN." (PMID 36291348, 2022). "Compared with that in normal brain tissues, the SCIN mRNA expression was higher in various glioma types, including diffuse astrocytoma, anaplastic astrocytoma, GBM, and oligodendroglioma." (PMID 36291348, 2022). "Clinicopathological analyses revealed that an elevated expression of SCIN in glioma patients was linked to an increased WHO grade and a poor survival, moreover, SCIN expression was positively correlated with MMP2 and MMP9 expressions." (PMID 36291348, 2022). "The Kaplan–Meier survival analysis of our clinical samples showed that an overexpression of SCIN, MMP2, and MMP9 were associated with a poor prognosis of glioma patients, respectively." (PMID 36291348, 2022). "Uncovering the role of SCIN in the progression of a glioma brings us a step closer to developing a therapeutic target." (PMID 36291348, 2022). "For the aberrant expression of SCIN and its association with cell metastasis and poor prognosis, SCIN has been proposed as the therapeutic target of many types of cancers, such as CRC and glioma." (PMID 39108273, 2024). "Additionally, Wang’ study revealed that SCIN expression was correlated with immune infiltration, and outcomes of glioma patients." (PMID 39108273, 2024). "To test our hypothesis, we analyzed the relationship between SCIN expression and the survival of glioma patients." (PMID 36291348, 2022). "Considering the important role of SCIN and MMP2/9 in the occurrence and development of a glioma, we speculate that the high expression of SCIN combined with MMP2/9 may enhance the invasiveness of gliomas and lead to a more malignant tumor progression." (PMID 36291348, 2022). "Therefore, we investigated a comprehensive analysis to reveal the correlation between SCIN expression and immune infiltration in gliomas based on the TISIDB and TIMER databases." (PMID 36291348, 2022). "In the present study, SCIN has been identified as a new prognostic biomarker and associated with MMP2/9 expression and tumor immune infiltration in gliomas, which indicates that SCIN may be used as a target for glioma treatment." (PMID 36291348, 2022). "In addition, the expressions of SCIN, MMP2, and MMP9 were associated with glioma prognosis." (PMID 36291348, 2022). "SCIN may serve as a potential prognostic marker and an immune therapy target for glioma." (PMID 36291348, 2022). "In addition, the expression of SCIN was related to MMP2/9 in glioma." (PMID 36291348, 2022).
glioma (continued). "We observed that SCIN and MMP2/9 protein expressions were upregulated significantly in glioma samples compared with normal brain tissues and progressively increased with the glioma grade." (PMID 36291348, 2022). "The results verified that the protein expression of SCIN and MMP2/9 were upregulated significantly in glioma tissues compared with normal brain tissues and were higher in high-grade (Grade III–IV) gliomas than in a low-grade (Grade II) glioma." (PMID 36291348, 2022). "We found that SCIN and MMP2/9 were upregulated in the primary glioma, SCIN had an excellent correlation with MMP2 and MMP9, and these proteins were closely related to the prognosis of a glioma." (PMID 36291348, 2022). "Our study demonstrated that SCIN expression was high and correlated with MMP2/9, a poor prognosis, and immune cell infiltration in gliomas." (PMID 36291348, 2022). "Given the association between the high SCIN expression and glioma grade, we speculated that SCIN could be a negative prognostic biomarker for the glioma outcome." (PMID 36291348, 2022). "We further performed Western blot analysis to examine the expressions of SCIN, MMP2, and MMP9 in 37 fresh frozen glioma samples and 6 normal tissues." (PMID 36291348, 2022). "SCIN and MMP2/9 are negative prognostic factors resulting in worsening glioma patients’ survival." (PMID 36291348, 2022).
head and neck cancer (3 papers, 2013 to 2022). A primary or metastatic malignant neoplasm affecting the head and neck. "While previous studies have shown increased expression of EPHRIN-A1 in head and neck cancers, the expression of SCINDERIN remains unestablished in these tumors." (PMID 24330498, 2013). "In the present work, we investigated the prognosis value of EPHRIN-A1 and SCINDERIN expression in head and neck carcinomas." (PMID 24330498, 2013). "Tumor tissue sections of 83 patients with head and neck cancer were assessed by immunohistochemistry for the expression of EPHRIN-A1, SCINDERIN, HLA class I molecules and the presence of CD8+ T cells." (PMID 24330498, 2013). "SCIN overexpression is commonly observed in several types of malignancies, but is not correlated with prognosis in head and neck cancers." (PMID 35490173, 2022).